ENSG00000239197
Synonyms: LOC124903615
Gene: Small nucleolar RNA gene on chromosome 15 (92,417,547 to 92,417,689, forward strand). Ensembl gene ENSG00000239197.
Gene Ontology:
Biological process: RNA processing
Cellular component: nucleolus
Homologues: Paralogues in human: SCARNA18 (64% identical), SCARNA18B (60% identical).